BRAF (B-Raf proto-oncogene, serine/threonine kinase)
Diseases named in the same sentence as BRAF in open-access papers (continued):
Sharing a sentence is not in itself a finding about the gene and the disease.
colorectal cancer (continued). "Further, high KLF5 expression was observed in BRAF‐mutant colorectal cancer." (PMID 30478887, 2019). "Diminished response to treatment with anti-EGFR monoclonal antibodies is found in KRAS-mutant or BRAF-mutant colorectal cancer but these mutations do not impair response to oxaliplatin- (OxPt) or cisplatin-based chemotherapy." (PMID 30792807, 2019). "According to recent reports, vitamin C selectively kills KRAS (kirsten rat sarcoma viral oncogene) - and BRAF (v-raf murine sarcoma viral oncogene homolog B)-driven colorectal cancer cells (CRCs) by inducing oxidative stress, suppressing glycolysis and the subsequent energy crisis, and cell death." (PMID 31357509, 2019). "In addition, a combination of the MEK inhibitor trametinib and panituzumab gave a response rate of 0% in BRAF mutant colorectal cancer." (PMID 31769426, 2019). "In addition, patients with colorectal cancer harboring KRAS, BRAF or PIK3CA mutations have poor prognosis compared to patients without these mutations." (PMID 31769426, 2019). "Therefore, it is necessary to further investigate the different response mechanisms between the two types of cancer and to develop innovative strategies to suppress MAPK activity in BRAF-mutant colorectal cancer." (PMID 31083627, 2019). "Although ERK1/2 activity counteracts the damages induced by an acute increase in intracellular calcium, in colorectal cancer, the oncogenic activation of BRAF/MEK/ERK1/2 induces a chronic ER stress that promotes cell survival and is associated with tumor progression and poor patient outcome." (PMID 31117237, 2019). "Furthermore, Vc has been suggested to kill KRAS and BRAF mutant colorectal cancer cells by targeting GAPDH20." (PMID 30774978, 2019). "Metastatic Lynch and Lynch-like colorectal cancers (in which BRAF mutations are largely absent) have increased DFS and OS compared with sporadic MSI colorectal cancer, although the typically younger age of patients with Lynch syndrome is a confounding factor." (PMID 31216061, 2019). "In addition to BRAF mutations, BRAF selective amplification was found to be the mechanism of acquired MEK inhibitor resistance by two groups in a colorectal cancer cell line in vitro, with MEK hyperactivation being observed in these resistant cells." (PMID 31126017, 2019). "Moreover, we will examine the enhanced the cell death by combined treatment with perifosine and trametinib or PD0325901 in other human colorectal cancer cell lines harboring KRAS, BRAF and PIK3CA mutation." (PMID 31769426, 2019). "A positive correlation of COX-2 expression and the presence of BRAF mutation were reported in human colorectal cancer, but have not been investigated in dogs." (PMID 30893857, 2019). "Moreover, as in colorectal carcinomas, MSI was strongly associated with BRAF V600E mutation and was observed in seven out of eight BRAF mutant cases." (PMID 31455041, 2019). "They concluded that IHC using anti-BRAF V600E (VE1) antibody is not a useful surrogate for detecting BRAF mutation in colorectal carcinoma." (PMID 29127628, 2019). "MSI cancers have a good prognosis but not all colorectal cancers with BRAF mutation and CIMP silence MLH1 and those that remain microsatellite stable (MSS) have a particularly poor prognosis." (PMID 29304767, 2018). "Interestingly, some colorectal cancer patients possess non-V600BRAF mutations, occurring in 2.2% of all patients tested and accounting for 22% of all identified BRAF mutations." (PMID 29652830, 2018). "Neither is BRAF V600E (GTG > GAG) explained by the dominant MMR-linked signature 6 in colorectal cancer." (PMID 29748584, 2018). "The efficacy of this approach is currently unclear across tumor types, as some mutations are only known to be prognostic for response in particular situations; some early attempts at matching therapies failed for this reason, e.g. the use of BRAF inhibitors in BRAF mutant colorectal cancer." (PMID 29707132, 2018).
colorectal cancer (continued). "Interestingly, in BRAF mutant tumors, BRAFV600E mutations—which are commonly observed in colorectal cancers—are rare and amount only to about 10% of these BRAF mutant tumors." (PMID 29652830, 2018). "To determine whether the loss of MLH1 protein expression associated with the A allele was a result of MLH1 promoter hypermethylation, we carried out methylation specific qPCR in all SSADs and BRAF mutant colorectal cancers." (PMID 29304767, 2018). "The present study, therefore, provides no conclusive evidence for a role of the SNP in KRAS or BRAF-mutated colorectal cancer development." (PMID 29694444, 2018). "In colorectal cancer (CRC), BRAF mutations influence tumour progression." (PMID 29988110, 2018). "Interestingly, 40% of those cancers with mutant PDE4B also possess mutations in the BRAF gene, in contrast to an incidence of only 8–10% BRAF-mutant carriers in the entire colorectal cancer population." (PMID 30188895, 2018). "A greater understanding of colorectal cancer biology followed by use of EGFR-targeted treatments has led to discovery of the importance of BRAF, PIK3CA, KRAS, and NRAS mutations in predicting a lack of response to EGFR-targeted therapy." (PMID 29254887, 2018). "Currently, KRAS and BRAF mutations are not seen as “only” altering signaling during the development of colorectal cancer." (PMID 29907857, 2018). "We clarified the clinical prevalence of ovarian metastases from colorectal cancers (CRCs) in 296 female patients with CRC and evaluated clinical outcomes with relation to their mutational profiles, such as BRAF/KRAS mutation and microsatellite instability (MSI) status." (PMID 29662660, 2018). "This study aimed to determine whether V600E mutant and wild type BRAF colorectal cancers exhibit distinct sensitivities to the dual BRAF inhibitor AZ304." (PMID 29755114, 2018). "Indeed, TRAP1 modulates the expression of the BRAF oncogene and the two proteins interact in colorectal cancer cells, being frequently co-expressed in human colorectal carcinomas." (PMID 29621137, 2018). "Since our results showed that miR-193a-3p was identified as a mutant-BRAF-specific miRNA, the worse outcome of colorectal cancer patients with the down-regulation of miR-193a-3p from anti-EGFR therapy may be confounded by the BRAF-mutation status." (PMID 29115941, 2017). "Moreover, colorectal cancer with MSI phenotype and a concomitant BRAF mutation indicates a sporadic tumor, thus excluding Lynch syndrome." (PMID 28953975, 2017). "Colorectal cancer patients with the BRAF mutation in their tumours show resistance to the Epidermal growth factor receptor (EGFR) inhibitor Cetuximab and their response to the BRAF inhibitor Vemurafenib is limited." (PMID 29479053, 2017). "In stage I colorectal cancer, BRAF mutations had a negative impact on both DFS (HR 3.936, 95% CI 2.120–7.306, P < 0.0001) and OS (HR 4.037, 95% CI 2.172–7.506, P < 0.0001)." (PMID 28583095, 2017). "V-raf murine sarcoma viral oncogene homolog B1 (BRAF), a principal downstream effector of the mitogen-activated protein kinase (MAPK)/extracellular signal-regulated kinase (ERK) pathway, is mutated in 5%–10% of colorectal cancer (CRC) cases." (PMID 29037218, 2017). "Of the 1001 consecutive colorectal cancer patients examined for RAS, PIK3CA, and BRAF tumor mutations using a multiplex kit (Luminex®), we studied 90 patients who received combination chemotherapy with bevacizumab as first-line treatment for metastatic colorectal cancer." (PMID 28068936, 2017).
colorectal cancer (continued). "Thus, the BRAF-mutation-like 58-gene signature would be an effective biomarker than sequencing BRAF p.V600E alone to select both actual BRAF mutation carriers and BRAF wild-type in the BRAF mutation-like subtype of colorectal cancer patients who may specifically benefit from Vinorelbine treatment." (PMID 29479053, 2017). "Candidate dysregulated miRNAs were selected in genome-wide miRNA expression array analysis using a screening set composed of 15 BRAF-mutated and 15 non-KRAS/BRAF-mutated colorectal cancers." (PMID 29115941, 2017). "Interestingly, proteasome inhibition has recently been suggested to represent a valuable target strategy in BRAF-mutant colorectal cancer." (PMID 28415818, 2017). "Finally, BRAF, which mediates CIMP in colorectal cancer, displayed a high proportion of positive associations (0.98) in COAD, but low proportions in SKCM (0.02) and thyroid carcinoma (THCA; 0.27)." (PMID 29125844, 2017). "Recently, several lines of evidence suggest that colorectal cancer containing a BRAF p.V600E mutation possesses more malignant potential when compared with other genotypes of colorectal cancer, including the KRAS/BRAF-wild-type tumor and the KRAS-mutated tumor." (PMID 29115941, 2017). "In addition, some mutated genes are druggable targets in one tumour entity but not in other tumour types (e.g. vemurafenib is ineffective in BRAF V600 mutant colorectal cancers)." (PMID 28545463, 2017). "In addition, the future clinical trials related to colorectal cancer, should specifically consider the eligibility of patients with concomitant KRAS and BRAF-mutated tumors." (PMID 28580315, 2017). "Median PFS/OS was 1.4/7.1 months in the BRAF-mutant colorectal cancer cohort, 1.5/4.7 months in the KRAS-mutant colorectal cancer 45 mg dose cohort, 3.5/9.1 months in the KRAS-mutant colorectal cancer 60 mg dose cohort, and 2.1/4.8 months in the biliary cohort." (PMID 28152546, 2017). "Mutated BRAF and KRAS oncogenes, both members of the Mitogen Activated Protein Kinase (MAPK) pathway, are respectively observed in approximately 10–20% and 35–42% of the sporadic colorectal cancers." (PMID 28125730, 2017). "In stage II and III colorectal cancer, BRAF mutations had a negative impact on DFS (HR 1.940, 95% CI 1.050–3.570, P = 0.0322) and OS (HR 3.320, 95% CI 1.820–6.070, P < 0.0001)." (PMID 28583095, 2017). "The detection of KRAS and BRAF mutations is a crucial step for the correct therapeuticapproach and predicting the epidermal growth factor receptor (EGFR)-targeted therapyresistance of colorectal carcinomas." (PMID 28580315, 2017). "In addition, we also investigated critical molecular events such as KRAS, BRAF and PIK3CA mutations and MSI status, all of which have been associated with colorectal cancer prognosis in order to adjusted our results." (PMID 26515606, 2016). "This particular primer was designed to selectively amplify DNA fragments containing the BRAF V600E single-nucleotide polymorphism, whose presence in cells predisposes patients to hereditary nonpolyposis colorectal cancer." (PMID 27244445, 2016). "Similar to the present results, a previous study evaluating the activity of proteasome inhibitors in BRAF V600E mutant colorectal cancer models also demonstrated that BRAF mutant cells were preferentially sensitive to treatment with proteasome inhibitors compared to BRAF wild-type cells." (PMID 27783987, 2016). "Somatic mutations in KRAS (codons 12, 13) and BRAF (V600E) in colorectal cancer predict poor prognosis and nonresponse to anti-EGFR antibodies." (PMID 27193446, 2016). "Mutations within RAS, BRAF and PI3K oncogenes have been frequently detected in colorectal cancer." (PMID 26802026, 2016).
colorectal cancer (continued). "ctDNA analysis indeed detected up to 12 distinct subclones, each harboring a different mutation in RAS-type family GTPases (RAS) or v-Raf murine sarcoma viral oncogene homolog B1 (BRAF) genes, in individual patients with colorectal cancer (CRC) after they had developed anti-EGFR therapy resistance." (PMID 26949746, 2016). "The progression of colorectal cancer (CRC) involves recurrent amplifications/mutations in the epidermal growth factor receptor (EGFR) and downstream signal transducers of the Ras pathway, KRAS and BRAF." (PMID 27562229, 2016). "In colorectal cancer, BRAF plays multifaceted roles in tumor progression, diagnosis, prognosis and may act as a predictor of response to combined targeted therapies." (PMID 26496026, 2015). "The other two samples retaining MMR expression exhibited MSI at 2/5 markers, lacked BRAF V600E mutations, but had no history of colorectal cancer." (PMID 26252492, 2015). "Given the known resistance mechanisms of MEK inhibition in colorectal cancer, we hypothesized that tumors with known KRAS/NRAS or BRAF mutations that were PIK3CA wild-type would exhibit greater sensitivity to MEK inhibition." (PMID 26439693, 2015). "In BRAF-mutant colorectal cancer cells, BRAF keeps EGFR inactive." (PMID 25885672, 2015). "In addition, we also investigated critical molecular events such as APC, KRAS, BRAF and PIK3CA mutations and MSI, all of which have been associated with colorectal cancer prognosis to justify the prognostic role of NEAT1." (PMID 26314847, 2015). "In colorectal cancer, the mitogen-activated protein kinase (MAPK) pathway is a commonly mutated pathway with 35–40% of patients having an activating mutation in KRAS and 5–10% of patients having an activating mutation in BRAF." (PMID 25688264, 2015). "In colorectal cancer KRAS exons 12 and 13 mutations drive de novo or acquired resistance to anti-EGFR therapy and KRAS and/or BRAF status may change with time between primary and metastatic lesions in colorectal cancer in 17% of patients." (PMID 26474073, 2015). "KRAS and BRAF are major oncogenic drivers of colorectal cancer (CRC)." (PMID 26299805, 2015). "Of 295 colorectal cancers, PRDM5 was mutated in only 6 (2%) cancers which were all BRAF wild type." (PMID 25613750, 2015). "In addition, we also investigated critical molecular events such as KRAS, BRAF and PIK3CA mutations and MSI, all of which have been associated with colorectal cancer prognosis to justify the independent prognostic role of NDRG4." (PMID 25749388, 2015). "Seven hundred fifty seven colorectal cancer cases were analyzed for BRAF mutations and the remaining 13 cases were not interpretable due to insufficient amount of DNA and other technical reasons." (PMID 25005754, 2014). "In contrast, colorectal cancers with this mutation do not respond to therapies targeting this specific BRAF mutation as a result of feedback activation of the epidermal growth factor receptor (EGFR)." (PMID 24782526, 2014). "The present study is first to provide data on frequency and type of KRAS and BRAF mutations of colorectal cancer in Albanian population; no data is present in the literature about this incidence." (PMID 25267307, 2014). "Colorectal cancers can be classified using mutations in oncogenes such as KRAS, BRAF and PIK3CA." (PMID 24885062, 2014). "In colorectal cancer targeted treatment of mutated BRAF is not feasible due to the innate resistance." (PMID 24298448, 2013). "In this present study, BRAF mutation was not correlated with sex, age (>50 years), location of colorectal cancers (right side, left side and rectum), stage of colorectal cancers or the number of multiple primary cancers (double; triple)." (PMID 24759670, 2013).
colorectal cancer (continued). "While the differences in BRAF mutation frequency between White, Black and Asian cohorts in colorectal cancer have not been previously reported, differences between other population groups have been noted." (PMID 24066160, 2013). "In contrast to these results, a recent guideline does not recommend testing for BRAF mutations in colorectal cancer patients before anti-EGFR treatment." (PMID 24298448, 2013). "This might be due to innate resistance mechanisms of colorectal cancers against the treatment solely targeting BRAF." (PMID 24298448, 2013). "KRAS, BRAF and PIK3CA mutations are frequently observed in colorectal cancer (CRC)." (PMID 23671647, 2013). "The finding of BRAF mutation being an independent factor of poor prognosis in male, but not in female colorectal cancer, both overall and in MSS tumours, is however novel and merits further study." (PMID 24020794, 2013). "BRAF mutation is associated with proximal location, higher age, female gender, MSI-H, high grade, and mucinous histology, and is a marker of poor prognosis in colorectal cancer." (PMID 24298448, 2013). "Colorectal cancers having a BRAF mutation are very unlikely to have Lynch syndrome, whereas those without a BRAF mutation should be further evaluated using other tests." (PMID 24759670, 2013). "KRAS, BRAF and PIK3CA mutations are commonly found in colorectal cancers." (PMID 23617638, 2013). "In addition to KRAS mutation, genetic alterations in NRAS, HRAS, BRAF, and RAF1 were found in colorectal cancer samples analyzed in this study." (PMID 23700467, 2013). "All colorectal carcinoma samples had been reported as BRAF and KRAS wildtype by q-PCR sequencing." (PMID 23922754, 2013). "Interestingly, BRAF mutations, which are predominantly mutually exclusive of mutant KRAS, have also been associated with resistance to anti-EGFR treatment in colorectal cancer." (PMID 23202889, 2012). "For instance, colorectal cancer patients who present mutations in KRAS or BRAF do not respond to panitumumab, a monoclonal antibody against EGFR, recently approved by FDA as a monotherapy against metastatic colorectal carcinoma." (PMID 23207070, 2012). "This study demonstrates that CIN commonly occurs in advanced BRAF mutant/MSS colorectal cancers where it may contribute to poorer survival, and further highlights molecular similarities occurring between these and BRAF wild type cancers." (PMID 23110075, 2012). "BRAF mutant/MSS cancers are an aggressive cancer type and this may be related to the findings that a BRAF mutation correlates with overexpression of the angiogenic factor, VEGFA, in colorectal cancer." (PMID 23110075, 2012). "Patient-derived colorectal cancer explants’ KRAS and BRAF mutation status." (PMID 22675560, 2012). "In contrast to the classical adenoma–carcinoma sequence, deregulation of the Wnt/beta-catenin pathway is rarely observed, whereas mutations of BRAF, and less frequently KRAS have been shown to be the initiating events in the serrated route to colorectal cancer." (PMID 23045412, 2012). "While BRAF mutation has been associated with an increased immune cell infiltration in colorectal carcinomas, adjustment for BRAF mutational status in our study did not significantly impact the findings shown in multivariable models." (PMID 22879926, 2012). "Using a similar approach, the use of two methylation panels as classifiers of colorectal cancer has been proposed: the first to identify highly methylated tumors (strongly correlated with BRAF) and a second to distinguish between intermediate (associated with KRAS) and low methylation groups." (PMID 21559209, 2011). "In addition, none of the previous studies has comprehensively examined potential confounding effect of key molecular biomarkers in colorectal cancer, including the CpG island methylator phenotype (CIMP), and KRAS, BRAF and PIK3CA mutations." (PMID 21949851, 2011).